MICOS10 (mitochondrial contact site and cristae organizing system subunit 10)
Description:
Component of the MICOS complex, a large protein complex of the mitochondrial inner membrane that plays crucial roles in the maintenance of crista junctions, inner membrane architecture, and formation of contact sites to the outer membrane.
Synonyms: C1orf151; MIC10; MINOS1; RP5-1056L3.2; FLJ36999; MIO10
Tractability: Antibody: UniProt predicts a signal peptide or a membrane-spanning region.
Gene: Protein-coding gene on chromosome 1 (19,484,403 to 19,629,821, forward strand). Ensembl gene ENSG00000173436.
Subcellular location: Mitochondrion inner membrane
Subcellular location (Human Protein Atlas): Mitochondria
Pathways (Reactome):
Organelle biogenesis and maintenance: Cristae formation
Gene Ontology:
Molecular function: protein binding
Biological process: cristae formation; inner mitochondrial membrane organization
Cellular component: MIB complex; MICOS complex; mitochondrial inner membrane; mitochondrion; SAM complex; mitochondrial crista junction
Genetic constraint (gnomAD): Loss-of-function variants: 3 observed, 5.44 expected, observed/expected ratio (o/e) 0.55, 90% interval 0.25 to 1.4. That is too few expected variants to judge how well the gene tolerates losing a copy. Missense variants: 56 observed, 36.91 expected, observed/expected ratio (o/e) 1.52, 90% interval 1.22 to 1.86. Synonymous variants: 21 observed, 15.44 expected, observed/expected ratio (o/e) 1.36, 90% interval 0.96 to 1.85.
Homologues: Orthologues: chimpanzee MICOS10 (100% identical), dog MICOS10 (96% identical), guinea pig MICOS10 (96% identical), mouse Micos10 (92% identical), rabbit MICOS10 (91% identical), rat Micos10 (88% identical).
Diseases named in the same sentence as MICOS10 in open-access papers:
MICOS10 is named in the same sentence as 3 diseases in open-access papers, as found by Europe PMC text mining. Sharing a sentence is not in itself a finding about the gene and the disease. The quoted sentences say what the papers report.
cancer (2 papers, 2020 to 2025). A tumor composed of atypical neoplastic, often pleomorphic cells that invade other tissues. "Currently, studies have shown that changes in MICOS subunits are associated with various cancers, but so far there are few reports specifically linking MICOS10 to cancer." (PMID 40620061, 2025). "SCP2, ABCD3, and MICOS10 were significantly negatively correlated with cancer‐associated fibroblasts (CAFs)." (PMID 40620061, 2025). "The study of SCP2, ABCD3, MICOS10, GCDH, and MTRF1L genes' immune infiltration and cancer correlation in CRC offers a fresh perspective." (PMID 40620061, 2025).
tumor (2 papers, 2021 to 2023). "In the TCGA datasets, BC tumor tissue showed elevated gene expression levels of IMMT, CHCHD6, CHCHD3, APOO, and MICOS10 as compared to normal tissue, while the APOOL level was decreased in tumor tissue as compared to normal tissue." (PMID 36899366, 2023).
MICOS10 also shares sentences with these, for which no sentence is quoted: breast carcinoma (1 paper).